BCL6B (BCL6B transcription repressor)
Diseases named in the same sentence as BCL6B in open-access papers (continued):
Sharing a sentence is not in itself a finding about the gene and the disease.
tumor (23 papers, 2014 to 2026). "We therefore conclude that Bcl6b plays a crucial role in regulating inflammation-associated GC initiation and development in vivo and that 5-Aza can be used as an anti-tumour compound through re-activation of Bcl6b." (PMID 31288844, 2019). "Importantly, BCL6B expression is negatively associated with advanced tumor stage, metastasis, and poor prognosis in HCC patients." (PMID 41049002, 2025). "BCL6B is critical for diverse biological processes, such as tumor suppression, immune regulation, stem cell self-renewal, and angiogenesis." (PMID 41049002, 2025). "As a transcriptional repressor, BCL6B regulates gene expression by modulating both oncogenic and tumor suppressive pathways, highlighting its potential as a biomarker and therapeutic target." (PMID 41049002, 2025). "Given its critical influence on both normal and malignant cell behavior, BCL6B is increasingly recognized as a pivotal regulator in tumor initiation and progression." (PMID 41049002, 2025). "Through modulation of these pathways, BCL6B influences tumor growth, metastasis, and resistance to therapy." (PMID 41049002, 2025). "In recent years, BCL6B has garnered increasing attention due to its critical involvement in various biological processes, including tumor suppression, immune modulation, stem cell maintenance, and angiogenesis." (PMID 41049002, 2025). "Treatment with 5-Aza-2'-deoxycytidine (5-Aza) reversed this methylation and reactivated BCL6B expression, exerting tumor-suppressive effects." (PMID 41049002, 2025). "Clinical data also suggest that BCL6B methylation correlates with advanced tumor stage, lymph node metastasis, and 5-fluorouracil (5-FU) resistance, indicating its value as a prognostic and predictive biomarker for chemotherapy response." (PMID 41049002, 2025). "Understanding the molecular mechanisms through which BCL6B affects tumor biology is therefore of significant clinical relevance." (PMID 41049002, 2025). "The development of cutting-edge models, including organoids and gene-edited animals, will be essential for validating BCL6B's roles in tumor suppression, immune regulation, and stem cell equilibrium." (PMID 41049002, 2025). "These epigenetic alterations lead to reduced expression of BCL6B, correlating with increased tumor proliferation, migration, and invasiveness." (PMID 41049002, 2025). "In many of these cancers, BCL6B expression is silenced through promoter CpG island hypermethylation, a common epigenetic mechanism that contributes to tumor suppressor gene inactivation." (PMID 41049002, 2025). "Reactivating BCL6B expression or reversing its promoter methylation has been shown to reduce tumor aggressiveness, underscoring its therapeutic potential." (PMID 41049002, 2025). "BCL6B exerts its biological functions—such as tumor suppression, immune modulation, stem cell maintenance, and angiogenesis—primarily through its role as a transcriptional repressor." (PMID 41049002, 2025). "BCL6B is reported to be involved in a diversity of biological functions, including tumor suppression, immune response, stem cell self-renew, and vascular angiogenesis, all of which are related to its function as a transcriptional repressor." (PMID 39075623, 2024). "This study provided compelling evidence that Bcl6b functions as a tumour suppressor to inhibit GC and suggested a novel inflammatory strategy to control GC." (PMID 31288844, 2019). "In summary, our study showed that BCL6B acts as a dominant tumour suppressor in GC and plays a crucial role in inflammatory response control in vivo." (PMID 31288844, 2019). "In recent studies, BCL6B has been identified as a novel tumour suppressor, which is silenced or downregulated by promoter hypermethylation and is associated with poor survival in colorectal carcinoma, hepatocellular carcinoma and GC." (PMID 31288844, 2019). "A greater than 30% increase in the incidence of tumour development upon BaP treatment was also observed in Bcl6b−/− mice." (PMID 31288844, 2019).
tumor (continued). "Images of gross gastric morphology (left), H&E staining (middle) and Pan-Cytokeratin immunostaining showed that tumour number and maximum size were significantly higher in Bap-treated Bcl6b−/− mice versus the control group." (PMID 31288844, 2019). "Recently, several novel putative tumour suppressors such as BCL6B 16, CPEB1 17, ZNF331 18, ZNF545 19 and CHIP 20 have been identified in GC." (PMID 30714150, 2019). "STXBP6 protein expression was downregulated in 91.43% of tumor tissues, BCL6B was downregulated in 88.57%, FZD10 was downregulated in 88.57%, and HSPB6 was downregulated in 91.43% (p <0.001, the original blots of western blots is shown in the S1–S8 Figs)." (PMID 30286088, 2018). "STXBP6 mRNA expression was downregulated in 66.67% of tumor tissues, BCL6B was downregulated in 69.23%, FZD10 was downregulated in 71.79%, and HSPB6 was downregulated in 74.36% (p <0.001)." (PMID 30286088, 2018). "Immunohistochemical staining of the HCC tissues showed predominant localization of the BCL6B protein in the cytoplasm in the adjacent non-tumor tissues but significant downregulation in HCC tissues." (PMID 25970780, 2015). "As a consequence, BCL6B was confirmed for its anti-tumor efficacy and was identified as a pivotal tumor suppressor gene in HCC." (PMID 25970780, 2015). "Combining immunotherapeutic approaches with BCL6B modulation could enhance anti-tumor immunity, while its regulation of vascular pathways offers innovative treatments for ischemic and vascular diseases." (PMID 41049002, 2025). "Functional studies demonstrated that restoring BCL6B expression in GC cell lines inhibited colony formation and viability, induced apoptosis, and significantly suppressed tumorigenesis in nude mice, confirming its role as a tumor-suppressive role in GC." (PMID 41049002, 2025). "Research on BCL6B, spanning tumor suppression, immune modulation, stem cell homeostasis, angiogenesis, molecular mechanisms, and therapeutic innovations, enhances our understanding of gene regulatory systems and support the development of innovative diagnostic and therapeutic strategies." (PMID 41049002, 2025). "In tumor biology, BCL6B has demonstrated notable tumor-suppressive activity." (PMID 41049002, 2025). "B-cell CLL/lymphoma 6 member B (BCL6B) operates as a sequence-specific transcriptional repressor within the nucleus, playing crucial roles in various biological functions, including tumor suppression, immune response, stem cell self-renew, and vascular angiogenesis." (PMID 39075623, 2024). "B-cell CLL/lymphoma 6 member B (BCL6B) is a tumor suppressor." (PMID 37391844, 2023). "A 25% reduction in the tumour incidence following 5-Aza treatment was observed in the wildtype mouse GC model compared to saline controls, while a minor curative effect (12.5% reduction) following 5-Aza treatment occurred in BaP-treated Bcl6b−/− mice." (PMID 31288844, 2019). "Finally, significant negative correlations were detected between the mRNA levels of BCL6B and inflammatory cytokines in human GC tissues; patients harbouring BCL6B-negetive and severe-inflammation GC tumours were found to exhibit the shortest survival time." (PMID 31288844, 2019). "Recently, researchers reported that BCL6B played a pivotal role as a potential tumour suppressor in GC, and the detection of methylation of the BCL6B DNA promoter might be deemed an independent biomarker for the prognosis of GC." (PMID 25008234, 2014). "Notably, four of these TFs—RUNX3, GABPB1, GABPA, and BCL6B—are known tumor suppressors." (PMID 40432923, 2025). "However, whether BCL6B functions as a key tumour suppressor and inflammatory regulator during the progression of gastric oncogenesis in vivo requires further study." (PMID 31288844, 2019). "Therefore, the importance of BCL6B as a potential tumour suppressor in GC should be highlighted." (PMID 25008234, 2014).
tumor (continued). "ZBTB28 (also known as BCL6B, ZNF62, and BAZF) is a recently discovered tumor suppressor gene, which belongs to the POK/ZBTB family and was originally discovered by cloning the homologous BCL6 gene." (PMID 33931087, 2021). "Mechanistically, BCL6B promotes apoptosis via activation of caspase cascades and cleavage of poly (ADP-ribose) polymerase (PARP), and inhibits metastasis by upregulating tumor suppressors such as E-cadherin, OB-cadherin, HTATIP2, and TRPM1, while downregulating VEGFA." (PMID 41049002, 2025). "Therefore, this study elucidates the mechanism by which the depalmitoyltransferase ABHD17C protects tumor cells from macrophage phagocytosis, which highlights the therapeutic potential of targeting the ABHD17C/BCL6B/CD24 signaling axis by macrophage-mediated innate immune pathway in PC." (PMID 42154583, 2026). "The methylation and expression validation results identified 4 candidate genes (STXBP6, BCL6B, FZD10, and HSPB6) that were significantly hypermethylated and downregulated in most of the tumor tissues compared with the noncancerous lung tissues." (PMID 30286088, 2018).
cancer (10 papers, 2015 to 2025). A tumor composed of atypical neoplastic, often pleomorphic cells that invade other tissues. "Non-invasive diagnostic tools, such as liquid biopsies detecting BCL6B promoter methylation in circulating plasma DNA, could enable early cancer detection and prediction of treatment response." (PMID 41049002, 2025). "Future research should aim to delineate additional signaling networks influenced by BCL6B and clarify its context-specific mechanisms across various cancer types." (PMID 41049002, 2025). "BCL6B expression was significantly decreased in these cancer tissues compared with paired normal tissues because of promoter methylation." (PMID 30286088, 2018). "Reduced expression of BCL6B is significantly in cancer tissue compared with adjacent tissue samples (p < 0.05)." (PMID 25909168, 2015). "Investigating its molecular mechanisms in greater depth may lead to innovative therapeutic approaches that leverage BCL6B's pro-apoptotic and anti-proliferative functions to combat cancer more effectively." (PMID 41049002, 2025). "In 21 cases of BCL6B reduced cancer samples, 18 cases were methylated." (PMID 25909168, 2015). "Among these genes, HMGA2, CLDN1, TFPI2, KIAA0101 and EGR1 are cancer related genes according to Diseases Association Analysis and increased expression of EGR1 was confirmed by further semi-quantitative RT-PCR, quantitative RT-PCR and western blot in BCL6B re-expressed HepG2 and SNU449 cells." (PMID 25909168, 2015). "BCL6B is methylated in 100% (19/19) of human HCC cell lines, 40.0% (20/50) of adjacent tissue samples and 86.6% (129/149) of primary cancer samples." (PMID 25909168, 2015). "BCL6B exhibits antitumor properties, including inhibition of proliferation, cell cycle arrest, induction of apoptosis, and suppression of epithelial-mesenchymal transition (EMT) and cancer stemness." (PMID 41049002, 2025).
BCL6B also shares sentences with these, for which no sentence is quoted: lung carcinoma (3 papers); renal cell carcinoma (2); autoimmune disease (1); cholangiocarcinoma (1); colon cancer (1); colorectal adenocarcinoma (1); coronary atherosclerosis (1); esophageal cancer (1); gastritis (1); hematologic malignancies (1); influenza infection (1); leukemia (1); lung adenocarcinoma (1); oligospermia (1); Pancreatic Cancer (1).